STUB1 (STIP1 homology and U-box containing protein 1)
Diseases named in the same sentence as STUB1 in open-access papers (continued):
Sharing a sentence is not in itself a finding about the gene and the disease.
Ataxia (continued). "The homozygous STUB1 knockout mice displayed ataxia and cognitive impairment, mimicking patients with SCAR16." (PMID 34565360, 2021). "CHIP deficiency has been linked to several diseases, and mutations in the human STUB1 gene are associated with recessive and dominant forms of spinocerebellar ataxias (SCAR16/SCA48)." (PMID 34630034, 2021). "Further Sanger sequencing of all exons and intron–exon boundary junctions of STUB1 in 249 unrelated patients with cerebellar ataxia was performed." (PMID 34565360, 2021). "Variants in STUB1 cause both autosomal recessive (SCAR16) and dominant (SCA48) spinocerebellar ataxia." (PMID 34070858, 2021). "One prime example of such ligases is CHIP encoded by the STUB1 gene and whose genomic alterations cause spinocerebellar ataxia." (PMID 34566579, 2021). "We further determine that Stub1 mutants found in Ataxia patients are defective in pexophagy induction." (PMID 33077711, 2020). "In accordance with this idea, we have found that Stub1 mutants from Ataxia patients are defective in their ability to initiate Stub1-mediated pexophagy." (PMID 33077711, 2020). "Taken together, our results demonstrate that STUB1 mutations can cause ARCA by novel mechanisms such as protein instability and impaired substrate binding, leading to ataxia and hypogonadism." (PMID 25258038, 2014). "Our results show for the first time that STUB1 ataxia occurs also outside of Chinese populations (frequency 1.8% of non-Friedreich recessive ataxias), and expand the mutational spectrum of this disease." (PMID 24742043, 2014). "In sum, this frequent combination of ataxia with pyramidal tract damage indicates that STUB1 ataxia should be added to the differential diagnosis of the rapidly increasing list of “spastic ataxia” spectrum disorders." (PMID 24742043, 2014). "Here we show that STUB1-ataxia is not limited to Chinese populations, but can be observed also in Caucasian ataxia patients (frequency: 1.8% of non-Friedreich recessive ataxias)." (PMID 24742043, 2014). "Currently, POLR3A, POLR3B, OTUD4, STUB1, PNPLA6, and RNF216 are all genes associated with CHH syndromes and cerebellar ataxia, with clinical manifestations that can vary and may present with infant or adult onset." (PMID 40508017, 2025). "We further investigated the mutation frequency of STUB1 in a cohort of ataxia patients without a known molecular diagnosis." (PMID 34565360, 2021). "A variety of heterozygous missense or deletion variants in STUB1 contributing to SCA48 have been reported to be located throughout the coding sequence, without evidence of any genotype–phenotype correlation in the severity of cerebellar ataxia." (PMID 34565360, 2021). "These suggest that in Ataxia patients Stub1-mediated pexophagy will be defective." (PMID 33077711, 2020). "Remarkably, STUB1 mutations were found in nearly 2% of Caucasian patients with degenerative ataxia, and these mutations appeared to be specific to the ataxia phenotype and not rare ubiquitous polymorphisms." (PMID 31619515, 2019). "Whole exome sequencing on an index patient with sporadic early-onset ataxia, followed by Sanger sequencing in all family members, was used to identify causative variants as well as to rule out alternative genetic hits and intronic STUB1 variants." (PMID 33811518, 2021). "Importantly, we demonstrate here that STUB1 causes the Gordon Holmes syndrome (early onset ataxia plus hypogonadism) not in isolation, but rather as part of a broad multisystemic neurodegenerative process." (PMID 28193273, 2017). "There was no family history of ataxia, so clinical whole-genome sequencing was performed, and a heterozygous variant of unknown significance was observed in the STUB1 gene encoding for a c.155C > G mutation that results in a single point mutation in the CHIP protein (A52G)." (PMID 35398354, 2022).
lung carcinoma (24 papers, 2012 to 2025). "In breast and lung cancer, STUB1 interacts with various proteins through its ubiquitination-dependent proteasome activity." (PMID 39061176, 2024).
gastric cancer (17 papers, 2016 to 2025). A primary or metastatic malignant neoplasm involving the stomach. "STUB1 is recognized as a tumor suppressor in liver, prostate, lung, and gastric cancers through the degradation of key oncogenic proteins, such as JMJD1A, YAP1, AR1, and YTHDF2." (PMID 40859326, 2025). "In the meantime, RNF112 and STUB1 expression was significantly suppressed in gastric cancer compared with adjacent paracancer tissues revealed by TCGA data." (PMID 37288663, 2023).
prostate carcinoma (17 papers, 2016 to 2024). A carcinoma that arises from epithelial cells of the prostate gland. "Here we further confirmed that knockdown of HSP70 in resistant prostate cancer cells significantly promotes STUB1 nuclear translocation by western blot; suggesting that HSP70 is critical in controlling STUB1 nuclear translocation." (PMID 34272475, 2021). "Our findings related to the HSP70/STUB1/AR-V7 complex are important as this mechanism may represent a general chaperone–ubiquitin–proteasome mechanism for the regulation of AR variants protein stability that may involve in treatment resistance in advanced prostate cancer." (PMID 30446660, 2018). "Here, the authors show that AR-V7 protein stability is regulated by HSP70/STUB1 complex-mediated proteostasis which confers drug resistance in late stage prostate cancer." (PMID 30446660, 2018). "We found that STUB1 expression was significantly reduced in AR-V7 positive prostate cancer cells, such as C4-2B MDVR, C4-2B AbiR, CWR22Rv1, and VCaP cells compared to the AR-V7 negative LNCaP cells." (PMID 30446660, 2018). "In conclusions, we have identified a new AR/AR-V7 degrader named ARVib and showed that ARVib effectively degrades AR/AR-V7 protein through the ubiquitin-proteasome pathway mediated by the HSP70/STUB1 complex and attenuates AR/AR-V7 downstream target gene expression in prostate cancer cells." (PMID 34272475, 2021). "Notably, the proteasome activity is significantly suppressed in enzalutamide and abiraterone-resistant prostate cancer cells and the E3 ligase STUB1 and its binding chaperone protein HSP70 might control the AR-V7 proteostasis and confer the resistance." (PMID 30446660, 2018). "However, when HSP70 is up-regulated as in advanced prostate cancer, it occupies the “SELILKR” binding motif on native N-Myc protein and prevent the access of STUB1 possibly through steric hindrance." (PMID 39103353, 2024). "Ubiquitin proteasome activity is suppressed in enzalutamide resistant prostate cancer cells, and the heat shock protein 70/STIP1 homology and U-box-containing protein 1 (HSP70/STUB1) machinery are involved in androgen receptor (AR) and AR variant protein stabilization." (PMID 36773708, 2023).
pancreatic cancer (14 papers, 2014 to 2025). "The functions of STUB1 as an oncogene in non-small cell lung, breast, renal cell, oral, gastric, head and neck, and pancreatic cancers." (PMID 39267107, 2024). "Inversely, proteins such as SCAMP3, whose mRNA transcript abundance was found to be increased in normal tissues relative to RCC tissues, and STUB1, which is considered a tumor suppressor in pancreatic cancer, were enriched in HK2 EVs relative to RCC EVs." (PMID 34331598, 2021).
Alzheimer disease (11 papers, 2013 to 2025). A progressive, neurodegenerative disease characterized by loss of function and death of nerve cells in several areas of the brain leading to loss of cognitive function such as memory and language. "To further investigate the expression patterns and coordination of BAG2, STUB1, HSC70, and MAPT in Alzheimer’s disease patients, we performed a WGCNA analysis." (PMID 37251806, 2023). "Based on the literature survey and Uniport database findings, this article focuses on the effects on the protein folding and degradation system and Alzheimer’s disease when the molecular network consisting of BAG2, HSC70, STUB1 and MAPT is dysregulated." (PMID 37251806, 2023). "We performed a Weighted Gene Co-expression Network Analysis (WGCNA) to investigate the expression patterns and coordination of BAG2, STUB1, HSC70, and MAPT in Alzheimer’s disease (AD) patients." (PMID 37251806, 2023). "In this study, the alterations in the expression of four genes were examined in individuals at various stages of Alzheimer’s disease to elucidate the role of BAG2, HSC70, STUB1 in folding and degradation of Tau in disease pathogenesis and progression." (PMID 37251806, 2023).
glioma (11 papers, 2015 to 2025). A benign or malignant brain and spinal cord tumor that arises from glial cells (astrocytes, oligodendrocytes, ependymal cells). "Conversely, in high-grade glioma tissues, there was a notable upregulation in STUB1 expression, whereas SVIP expression exhibited a decline." (PMID 39138166, 2024). "On a comparison of these two cohorts, we found STUB1 and YWHAH proteins dysregulated in Grade II glioma patients." (PMID 26370624, 2015). "Therefore, we analyzed the correlation between STUB1 and IGFBP-2 in the CGGA database, and observed a positive correlation between them in gliomas." (PMID 39138166, 2024).
Cognitive impairment (10 papers, 2014 to 2025). Abnormal cognition is characterized by deficits in thinking, reasoning, or remembering. "Evidence in clinical familial cases have also demonstrated that mutations in STUB1/CHIP were identified in patients with ARCA along with cognitive impairment." (PMID 29491882, 2018). "The six STUB1 variants have been identified and reported as pathogenic in individuals with SCAR16; E28K and N65S were identified in two families with ARCA and cognitive impairment by our group." (PMID 28396517, 2017).
Spinocerebellar Ataxia Autosomal Recessive 16 (10 papers, 2017 to 2022). "So far, more than 30 STUB1 mutations have been identified in patients with autosomal recessive spinocerebellar ataxia type 16 (SCAR16)." (PMID 34630034, 2021). "Spinocerebellar ataxia autosomal recessive 16 (SCAR16) is caused by coding mutations in STUB1, a gene that encodes the multifunctional enzyme CHIP (C terminus of HSC70-interacting protein)." (PMID 31619515, 2019). "Coding mutations in STUB1 cause a rare multi-organ disease, and is now identified as SCAR16 (autosomal recessive spinocerebellar ataxia 16, OMIM: 615768)." (PMID 30111698, 2018). "Biallelic STUB1 mutations resulting in aberrant CHIP have been identified in patients with clinical features of autosomal recessive spinocerebellar ataxia-16 (SCAR16)." (PMID 29581457, 2018). "Recently, it was shown that recessive mutations in STUB1 can cause spinocerebellar ataxia, autosomal recessive 16 (SCAR16) in some families." (PMID 28396517, 2017). "Spinocerebellar ataxia, autosomal recessive 16 (SCAR16) is caused by biallelic mutations in the STIP1 homology and U-box containing protein 1 (STUB1) gene encoding the ubiquitin E3 ligase and dimeric co-chaperone C-terminus of Hsc70-interacting protein (CHIP)." (PMID 28396517, 2017). "In addition to SCA48, autosomal recessive mutations in STUB1 also causes spinocerebellar ataxia autosomal recessive type 16 (SCAR16)." (PMID 35398354, 2022).
leukemia (9 papers, 2016 to 2025). A malignant (clonal) hematologic disorder, involving hematopoietic stem cells and characterized by the presence of primitive or atypical myeloid or lymphoid cells in the bone marrow and the blood. "For instance, the ubiquitin ligase STUB1 regulates the stability and activity of RUNX1 in leukemia; RNF38 promotes RUNX1 ubiquitination and enhances RUNX1-mediated erythroid transcriptional program inhibition; while FZR1 regulates ubiquitin-dependent degradation of RUNX1 in aplastic anemia." (PMID 36949071, 2023). "Transduction of UBR1 and UBR2 was sufficient to rescue leukemia cells from shSOD2-mediated sensitization to asparaginase while transduction of FBXW7 or STUB1 could not reverse this effect." (PMID 40131931, 2025).
melanoma (9 papers, 2010 to 2025). A malignant, usually aggressive tumor composed of atypical, neoplastic melanocytes. "First, we used a syngeneic transplantable murine melanoma model, in which we differently labeled wildtype and Stub1-deficient B16F10-dOVA cells with either EGFP or mCherry, respectively." (PMID 35395848, 2022). "Having observed an enhanced sensitivity of STUB1-deficient melanoma cells to cytotoxic T cell-derived IFNγ in vitro, we next investigated the effects of enhanced IFNγ signaling and its relationship to anti-PD-1 treatment in vivo." (PMID 35395848, 2022). "We first established Stub1-deficient murine melanoma cell lines in which we were able to reiterate our findings from human cell lines in vitro." (PMID 35395848, 2022). "We therefore profiled transcriptomic changes in wildtype and STUB1-deficient melanoma cells 8 h after T cell attack." (PMID 35395848, 2022). "Indeed, at concentrations where wildtype melanoma cells were barely affected by IFNγ or T cell attack, STUB1-deficient melanoma cells were eliminated efficiently." (PMID 35395848, 2022). "Collectively, these data show that the strong basal and dynamic induction of IFNγ-R1 expression by STUB1 inactivation results in intensified IFNγ signaling and consequently, IFNγ-dependent sensitization of melanoma cells to cytotoxic T cells in vitro." (PMID 35395848, 2022). "To determine the relevance of these residues for the STUB1-mediated regulation of IFNγ-R1 and JAK1, we generated melanoma cell clones deficient in both IFNGR1 and JAK1 (IFNGR1-KO + JAK1-KO) in either a wildtype or STUB1-deficient background." (PMID 35395848, 2022). "More precisely, we identified interaction links of PKA to STUB1 in A375 melanoma cells, in KM12 and SW480 colon cancer cells, in osteosarcoma cells (U2OS) and in the only tested patient tissue (glioblastoma)." (PMID 31189917, 2019). "To determine whether STUB1 functions as a negative regulator of IFNγ-R1 expression beyond melanoma, we depleted it by Cas9-mediated knockout from cell lines originating from different tumor indications, and assessed the effect on the expression of IFNγ-R1." (PMID 35395848, 2022). "We performed the same IFNγ-R1 regulator screen in a second human melanoma cell line, SK-MEL-23, which was similar in quality and again identified STUB1 and UROD." (PMID 35395848, 2022).
hypogonadism (8 papers, 2014 to 2025). A disorder characterized by decreased function of the gonads. "Combined with our studies demonstrating that mice lacking the expression of CHIP display motor deficiencies and some aspects of the hypogonadism observed in patients with STUB1 mutations, our CHIP knockout mouse represented the first animal model of SCAR16." (PMID 30222779, 2018). "Recently, reports have linked mutations in genes involved in ubiquitination (RNF216, OTUD4, STUB1) to ARCA with hypogonadism." (PMID 25258038, 2014). "This evidence suggests that STUB1 activities cannot be fulfilled by other E3 ubiquitin ligases in some neuronal cell types and, possibly, in gonadotropic cells, although it is not clear whether the hypogonadism is due to hypothalamic or pituitary defects." (PMID 36594740, 2023).
atherosclerosis (7 papers, 2020 to 2026). A disease characterized by the build-up of fatty material and calcium deposition in the arterial wall resulting in partial or complete occlusion of the arterial lumen. "Based on the role STUB1 plays in regulating the stability of Foxp3, targeting STUB1 may be beneficial in the inflammation conditions of atherosclerosis." (PMID 33193911, 2020).
diabetes (7 papers, 2010 to 2025). "STUB1 has been shown to regulate diabetes through the degradation of INSR, and we demonstrated another mechanism to control insulin signaling." (PMID 38970167, 2024).
esophageal squamous cell carcinoma (7 papers, 2014 to 2025). Esophageal squamous cell carcinoma (ESCC) is a type of esophageal carcinoma (EC) that can affect any part of the esophagus, but is usually located in the upper or middle third. "The anti-HIV drug elvitegravir inhibited metastasis by directly targeting METTL3 and enhancing stress-inducible phosphoprotein 1 homology and U-box containing protein 1 (STUB1)-mediated proteasomal degradation in esophageal squamous cell carcinoma (ESCC)." (PMID 37391814, 2023). "Conversely, the overexpression of STUB1 has been linked to negative outcomes and tumor advancement in certain cases, such as renal clear cell, gallbladder, and esophageal squamous cell carcinoma." (PMID 39267107, 2024).
heart failure (7 papers, 2016 to 2025). Inability of the heart to pump blood at an adequate rate to meet tissue metabolic requirements. "Collectively, these findings demonstrate that Asb10 stabilizes HSP70 via competitively inhibiting STUB1-mediated ubiquitin-dependent degradation, thereby exacerbating cardiac hypertrophy, highlighting the role of Asb10 in hemodynamic stress-induced cardiac hypertrophy and heart failure." (PMID 40399264, 2025). "Our data further showed that Asb10 prevents HSP70 from undergoing STUB1-mediated ubiquitination and degradation, and HSP70-associated cardiac inflammation and HDAC2 phosphorylation may contribute to Asb10 overexpression-induced pathological cardiac hypertrophy and heart failure." (PMID 40399264, 2025).
cardiac hypertrophy (6 papers, 2012 to 2025). "Overexpression of Asb10 aggravates pressure overload-induced pathological cardiac hypertrophy by directly interacting with HSP70 and competitively inhibiting STUB1-mediated ubiquitin-dependent degradation of HSP70." (PMID 40399264, 2025).
glioblastoma (5 papers, 2018 to 2024). The most malignant astrocytic tumor (WHO grade IV). "In our study, SVIP expression levels were decreased and STUB1/CHIP expression levels were increased in glioblastoma, so that the two were out of balance compared with non-tumor tissues." (PMID 39138166, 2024).
hepatocellular carcinoma (5 papers, 2016 to 2024). A malignant tumor that arises from hepatocytes. "Heat shock protein 90 beta (HSP90β) promotes the progression of hepatocellular carcinoma (HCC) by suppressing STIP1 homology and U‐box‐containing protein 1 (STUB1)‐induced YTHDF2 ubiquitination, which may inaugurate a novel intervention strategy for the treatment of HCC." (PMID 37515378, 2023).
neuroblastoma (5 papers, 2015 to 2022). Neuroblastoma (NB) is the most common solid, extracranial childhood tumor. "In mammalian neuroblastoma cells, overexpression of UBE4B and STUB1, which encodes the E3 ligase CHIP, increases the ubiquitination and degradation of Tau." (PMID 34078905, 2021). "In mammalian neuroblastoma cells, UBE4B-mediated Tau clearance was accelerated by co-expression of STUB1, which encodes an ubiquitin E3 ligase for Tau." (PMID 34078905, 2021). "In addition, pepstatin A (PEPA) alone and E64D plus PEPA (E64D + PEPA), autophagy inhibitors, significantly inhibited Tau degradation, suggesting that ALS was the major pathway of UBE4B and STUB1-mediated Tau degradation in neuroblastoma cells." (PMID 34078905, 2021). "In mammalian neuroblastoma cells and a mouse tau overexpression model, UBE4B, and STUB1 E3 ligases ubiquitinated Tau proteins and induced autophagy-mediated Tau degradation." (PMID 34078905, 2021). "To determine the primary pathway of UBE4B and STUB1-mediated Tau degradation, we co-overexpressed UBE4B and STUB1 with Tau in neuroblastoma cells, and treated the cells with either the UPS inhibitor MG132 or the ALS inhibitors." (PMID 34078905, 2021). "Since the knockdown of STUB1 in neuroblastoma cell lines showed no change in Tau levels in the presence of UBE4B, we further examined the importance of STUB1 in the in vivo Drosophila model system." (PMID 34078905, 2021).